GALNT7 (polypeptide N-acetylgalactosaminyltransferase 7)
Description:
Glycopeptide transferase involved in O-linked oligosaccharide biosynthesis, which catalyzes the transfer of an N-acetyl-D-galactosamine residue to an already glycosylated peptide. In contrast to other proteins of the family, it does not act as a peptide transferase that transfers GalNAc onto serine or threonine residue on the protein receptor, but instead requires the prior addition of a GalNAc on a peptide before adding additional GalNAc moieties. Some peptide transferase activity is however not excluded, considering that its appropriate peptide substrate may remain unidentified.
Synonyms: GalNAc-T7; GalNAcT7
Tractability: Small molecule: a structure with a bound ligand is known. Antibody: UniProt predicts a signal peptide or a membrane-spanning region. PROTAC: ubiquitination databases record sites on it; its protein half-life has been measured.
Gene: Protein-coding gene on chromosome 4 (173,168,811 to 173,323,967, forward strand). Ensembl gene ENSG00000109586.
Subcellular location: Golgi apparatus membrane
Subcellular location (Human Protein Atlas): Golgi apparatus; Nucleoplasm
Pathways (Reactome):
Metabolism of proteins: O-linked glycosylation of mucins
Gene Ontology:
Molecular function: polypeptide N-acetylgalactosaminyltransferase activity
Biological process: carbohydrate metabolic process; protein O-linked glycosylation; protein O-linked glycosylation via N-acetyl-galactosamine
Cellular component: extracellular exosome; membrane; Golgi apparatus; Golgi membrane
Genetic constraint (gnomAD): Loss-of-function variants: 15 observed, 27.63 expected, observed/expected ratio (o/e) 0.54, 90% interval 0.36 to 0.84. The upper end of that interval is the gene's LOEUF score, 0.84, which puts it in group 3 of 6, group 1 being the genes least tolerant of losing a copy. Missense variants: 335 observed, 385.13 expected, observed/expected ratio (o/e) 0.87, 90% interval 0.8 to 0.95. Synonymous variants: 126 observed, 137.2 expected, observed/expected ratio (o/e) 0.92, 90% interval 0.79 to 1.07.
Homologues: Orthologues: chimpanzee GALNT7 (99% identical), macaque GALNT7 (99% identical), dog GALNT7 (96% identical), rat Galnt7 (95% identical), mouse Galnt7 (95% identical), pig GALNT7 (94% identical), guinea pig GALNT7 (91% identical), rabbit GALNT7 (82% identical), zebrafish galnt7 (79% identical), tropical clawed frog galnt7 (78% identical), Drosophila melanogaster Pgant5 (31% identical), Drosophila melanogaster Pgant9 (30% identical), and 2 more. Paralogues in human: GALNT1 (33% identical), GALNT10 (33% identical), GALNTL6 (32% identical), GALNT13 (32% identical), GALNT4 (30% identical), GALNT6 (29% identical), GALNT11 (29% identical), GALNT5 (29% identical), GALNT12 (28% identical), GALNT3 (28% identical), GALNT14 (27% identical), GALNT15 (27% identical), and 7 more.
Diseases named in the same sentence as GALNT7 in open-access papers:
GALNT7 is named in the same sentence as 44 diseases in open-access papers, as found by Europe PMC text mining. Sharing a sentence is not in itself a finding about the gene and the disease. The quoted sentences say what the papers report.
cervical cancer (18 papers, 2013 to 2024). A primary or metastatic malignant neoplasm involving the cervix. "GALNT7 expression is a well-described hallmark of many cancers such as cervical cancer, pancreatic cancer, and laryngocarcinoma." (PMID 29970122, 2018). "For example, miR-125a-5p inhibits the proliferation and invasion of cervical cancer cells by inhibiting GALNT7." (PMID 39493373, 2024). "MiR‐125a‐5p, for example, inhibits cervical cancer cell proliferation both in vivo and in vitro by targeting GALNT7 to inhibit the signaling cascade EGFR/PI3K/AKT after significantly down‐regulating such miRNA in cervical cancer cells." (PMID 36305754, 2023). "Few recent studies have shown the crucial role of GALNT7 in tumorigenesis of colorectal cancer, cervical cancer, and prostate cancer." (PMID 37633945, 2023). "Evidence from non-coding RNAs has indicated that, among cancer-specific miRNAs, miR-214 suppresses cell growth and invasion through targeting the oncogenic GALNT7 gene in human cervical cancer." (PMID 34485140, 2021). "Previous studies indicate that increased expression of lncSnhg7 and/or GALNT7 regulates cell proliferation in glioma cells, cervical cancer HeLa and Caski cells, and colon cancer cell lines." (PMID 35087510, 2021). "Abnormal expression of GALNT7 has been found in many types of cancer, and MiR-125a-5p is shown to inhibit the formation of cervical cancer by inhibiting the expression of GALNT7 in vivo." (PMID 34819077, 2021). "One study in cervical cancer tissues showed an increase in N-acetylgalactosaminyltransferase 7 (GALNT7) compared to adjacent normal cervical tissues, although the specific characteristic of GalNAc-modified proteins was not available." (PMID 34485140, 2021). "And miR-125a-5p played a cancer suppressor gene role by directly bounding to GALNT7 to repress the expression of GALNT7 and participated in the regulation of cervical cancer progression." (PMID 32308562, 2020). "Similar to the effect of miR-125a-5p mimic, silencing GALNT7 inhibited proliferation and invasion of cervical cancer cells." (PMID 32308562, 2020). "MiR-125a-5p directly targeted and post-transcriptionally downregulated GALNT7 that was strongly upregulated in cervical cancer tissues and cell lines." (PMID 32308562, 2020). "In conclusion, miR-125a-5p suppressed cervical cancer progression by post-transcriptionally downregulating GALNT7 and inactivating the EGFR/PI3K/AKT pathway." (PMID 32308562, 2020). "And the mRNA and protein levels of GALNT7 in four cervical cancer cell lines were also higher than those in NCEC cells." (PMID 32308562, 2020). "RT-qPCR was used to detect the expression of miR-125a-5p and GALNT7 in cervical cancer tissues and cell lines." (PMID 32308562, 2020). "The mRNA level of GALNT7 significantly increased in cervical cancer tissues compared with adjacent tissues (P < 0.01)." (PMID 32308562, 2020). "GALNT7 upregulation has previously been shown to be involved in growth and invasion in cervical cancer and its downregulation increases metastasis formation in melanoma cells." (PMID 32582529, 2020). "In our study, GALNT7 was found as a downstream target of miR-125a-5p and participated in the metabolism of cervical cancer." (PMID 32308562, 2020). "Overall, these data suggested that GALNT7 played an important role in cervical cancer progression via EGFR/PI3K/AKT pathway." (PMID 32308562, 2020). "The knockdown of GALNT7 in cervical cancer cell lines inhibited cell proliferation, migration, and invasion." (PMID 30563114, 2018). "Another study also showed that miR-214 is downregulated in cervical cancer tissue, and polypeptide N-acetylgalactosaminyltransferase 7 (GALNT7) was also identified as a target of this miRNA." (PMID 30563114, 2018). "Several studies have reported the function of GALNT7 in the regulation of hepatocellular carcinoma and cervical cancer." (PMID 29970122, 2018).
cervical cancer (continued). "Overexpression of GALNT7 is associated with carcinogenesis and metastasis in laryngeal squamous cell carcinoma (LSCC), hepatocellular carcinoma, cervical cancer, superficial spreading melanoma (SSM) and nodular melanoma (NM)." (PMID 27322213, 2016). "GALNT7 is frequently up-regulated in cervical cancer associated with cervical cancer cell proliferation, migration, and invasion; yet down regulation of GALNT1 and GALNT7 is associated with enhanced melanoma cell migration, invasion and immunosuppression." (PMID 25730904, 2015). "At the same time, GALNT7 is reported to be up-regulated in many cancers such as laryngeal carcinoma, cervical cancer, and pancreatic cancer." (PMID 25809707, 2015). "miR-214 negatively regulates N-acetylgalactosaminyltransferase 7 (GALNT7) and distinctly inhibits cervical cancer cell proliferation, migration, and invasion." (PMID 23773282, 2013). "The expression of GALNT7 in cervical cancer is often upregulated and promotes tumor proliferation." (PMID 34819077, 2021). "Our results showed that GALNT7 also highly expressed in cervical cancer cells, and downregulation of GALNT7 could inhibit tumor proliferation and invasion." (PMID 32308562, 2020). "All results suggested that miR-125a-5p could inhibit the growth of cervical cancer in vivo by suppressing the expression of GALNT7." (PMID 32308562, 2020). "PD153035 and LY294002 respectively inhibit EGFR and PI3K, which could inhibit GALNT7′s promoting effect on the proliferation and invasion of cervical cancer cells." (PMID 32308562, 2020). "Moreover, the role of miR-125a-5p inhibited tumor formation in cervical cancer by suppressing the expression of GALNT7 in vivo." (PMID 32308562, 2020). "Moreover, we also detected the levels of GALNT7 in cervical cancer tissues and cervical cancer cell lines." (PMID 32308562, 2020). "In addition, miR-125a-5p could inhibit the progression of cervical cancer by down-regulating the activity of GALNT7 and the EGFR/PI3K/AKT signaling pathway." (PMID 36313765, 2022). "However, the interaction between miR-125a-5p and GALNT7 in cervical cancer is unclear." (PMID 32308562, 2020). "It has been reported that EGFR/PI3K/AKT pathway was one of the most enriched pathways involved in the development of cervical cancer, so we investigated the role of EGFR/PI3K/AKT pathway in the development of GALNT7-mediated cervical cancer." (PMID 32308562, 2020). "Downregulation of miR-214 in cervical cancer has been reported by several groups, and miR-214 has been shown to inhibit the growth, migration, and invasion of cervical cancer cells by targeting oncogenes MEK3, JNK1, Plexin-B1, and GALNT7." (PMID 24614175, 2014). "MiR-214 has also been identified to be involvement of cervical cancer development by targeting MEK3, JNK1, GALNT7 and Plexin-B1." (PMID 24465927, 2014). "Likewise, down-regulation of miR-214 and up-regulation of its target gene GALNT7 have been documented in cervical cancer cells but not in adjacent normal tissues." (PMID 27322213, 2016).
colorectal cancer (16 papers, 2018 to 2025). A primary or metastatic malignant neoplasm that affects the colon or rectum. "Among dMMR/MSI colorectal cancers, GALNT7-Low status was associated with poor tumor differentiation but not with other clinicopathologic characteristics." (PMID 40824763, 2025). "In MSS colorectal cancers, GALNT7 expression was associated with survival in TCGA MSS (n = 430; P = 0.0160; HR = 0.58; 95% CI, 0.37–0.90) and AC-ICAM MSS (n = 224; P = 0.0164; HR = 0.56; 95% CI, 0.34–0.90) but not in GSE39582 MSS (n = 405; P = 0.4297; HR = 0.87; 95% CI, 0.61–1.24)." (PMID 40824763, 2025). "Importantly, the strength of this prognostic association in MSI colorectal cancers is evident from the markedly lower HR values across all three cohorts, highlighting a robust correlation between higher GALNT7 expression and better survival." (PMID 40824763, 2025). "In contrast, among dMMR/MSI colorectal cancers, the GALNT7-Low subset exhibits high levels of tumor cell PD-L1 and poor prognosis, highlighting the need for more intensive therapeutic strategies beyond current clinical practice." (PMID 40824763, 2025). "In conclusion, GALNT7 expression stratified dMMR/MSI colorectal cancers into distinct subsets with differential tumor cell PD-L1 expression and diverse survival outcomes, highlighting its potential as a prognostic biomarker to guide treatment strategies." (PMID 40824763, 2025). "Among 52 dMMR/MSI colorectal cancers, 65.4% were classified as GALNT7-High, whereas only 21.3% of 567 pMMR/MSS colorectal cancers fell into the GALNT7-High category (P < 0.0001)." (PMID 40824763, 2025). "Lastly, our data suggest the existence of two molecularly defined subtypes within dMMR/MSI colorectal cancers based on GALNT7 expression, characterized by differential tumor cell PD-L1 levels and distinct survival outcomes." (PMID 40824763, 2025). "In our IHC analysis, Tn antigen levels were higher in GALNT7-High colorectal cancers than in GALNT7-Low colorectal cancers, with this association being most prominent in dMMR/MSI colorectal cancers and to a lesser extent in pMMR/MSS colorectal cancers." (PMID 40824763, 2025). "Among them, GALNT7 effectively stratified dMMR/MSI colorectal cancers into two molecularly distinct subsets, characterized by differential tumor cell PD-L1 expression and distinct survival outcomes." (PMID 40824763, 2025). "In this study, we investigated the intertumoral heterogeneity of dMMR/MSI colorectal cancers, and our findings indicate that GALNT7 expression serves as a robust prognostic biomarker in this subgroup." (PMID 40824763, 2025). "Third, among the five genes, GALNT7 was significantly upregulated in MSI colorectal cancers compared with MSS CRCs." (PMID 40824763, 2025). "One possibility is that the upregulation of GALNT7 in dMMR/MSI colorectal cancers directly contributes to the increased Tn antigen expression." (PMID 40824763, 2025). "Our findings indicate the existence of two molecularly defined subtypes within dMMR/MSI colorectal cancers based on GALNT7 expression, characterized by differential tumor cell PD-L1 levels and distinct survival outcomes." (PMID 40824763, 2025). "Based on the H-score, colorectal cancers were further classified into GALNT7-High (H-score, 8–12) or GALNT7-Low (H-score, 0–7) group." (PMID 40824763, 2025). "Although not statistically significant, mucinous histology was enriched in GALNT7-High colorectal cancers (P = 0.0565), which was consistent with the findings at transcriptional levels." (PMID 40824763, 2025). "It has been reported that SNHG7 acts as a ceRNA by sponging miR-34a, which controls the expression of the GALNT7 target gene and promotes the progression of colorectal cancer (CRC) via the PI3K/Akt/mTOR pathway." (PMID 39028420, 2024). "miR-363-3p regulates the expression of GALNT7 and promotes the occurrence and development of colorectal cancer." (PMID 39493373, 2024).
colorectal cancer (continued). "The PI3K/AKT/mTOR pathway is activated in colorectal cancer when GALNT7 is expressed at high levels, facilitating the disease spread." (PMID 37946148, 2023). "For example, one oncogenic, long noncoding (lnc)RNA (lncRNA-SNHG7) has been shown to sponge miR-34a, upregulating the expression of the oncogene GALNT7 in colorectal cancer." (PMID 31569404, 2019). "Given that the prognostic impact of GALNT7 and its inverse relationship with immune checkpoint expression were observed in MSI colorectal cancers at the transcriptional level, we further sought to investigate the clinicopathologic and prognostic role of GALNT7 at the protein level using IHC." (PMID 40824763, 2025). "Given that GALNT7 expression was associated with survival outcomes and differentially expressed between MSI and MSS colorectal cancers, we hypothesized that its prognostic significance may vary depending on MSI status." (PMID 40824763, 2025). "Intriguingly, and consistent with the findings from transcriptomic datasets, dMMR/MSI colorectal cancers with GALNT7-High expression exhibited a significantly lower frequency of tumor cell PD-L1 positivity (23.8%) compared with GALNT7-Low dMMR/MSI colorectal cancers (58.8%)." (PMID 40824763, 2025). "Therefore, prospective validation, particularly for the prognostic value of GALNT7 in independent dMMR/MSI colorectal cancer cohorts, is required." (PMID 40824763, 2025). "Given that the expression of GALNT7 had a prognostic impact, particularly in MSI colorectal cancers, we speculated that molecular and/or immune profiles might also differ according to GALNT7 levels within MSI colorectal cancers." (PMID 40824763, 2025). "To test this hypothesis, we conducted a series of in vitro assays using MSI colorectal cancer cell lines transfected with siRNAs targeting GALNT7." (PMID 40824763, 2025). "Although our analyses consistently demonstrated a favorable prognostic impact of high GALNT7 expression in dMMR/MSI colorectal cancers across multiple cohorts, the observational design precludes a definitive mechanistic explanation for this dMMR/MSI-restricted effect." (PMID 40824763, 2025). "IHC for GALNT7 may effectively identify a subset of dMMR/MSI colorectal cancers characterized by high GALNT7 expression and excellent prognosis." (PMID 40824763, 2025). "Our results warrant future clinical and mechanistic studies to determine whether dMMR/MSI GALNT7-Low colorectal cancers derive greater benefit from PD-1/PD-L1 blockade, alone or in combination with a CTLA-4, TIM-3, or LAG-3 inhibitor." (PMID 40824763, 2025). "Fifth, GALNT7 expression was inversely associated with PD-L1 expression at both the mRNA and protein levels, and this association was exclusively observed in dMMR/MSI colorectal cancers." (PMID 40824763, 2025). "However, the role of GALNT7 in dMMR/MSI colorectal cancers has remained largely unexplored." (PMID 40824763, 2025). "SNHG7/miR-34a may be involved in the progression of colorectal cancer through the GALNT7 pathway." (PMID 34819077, 2021). "Specifically, in MSI colorectal cancers, immune ESTIMATE, HAVCR2 (TIM-3), CD274 (PD-L1), LAG3 (LAG-3), and PDCD1 (PD-1) each showed significant inverse correlations with GALNT7 expression across the three cohorts." (PMID 40824763, 2025). "Most importantly, we observed a striking difference in the prognostic impact of GALNT7 IHC between dMMR/MSI and pMMR/MSS colorectal cancers." (PMID 40824763, 2025). "Conversely, we found a marked increase in Tn antigen H-score in GALNT7-High dMMR/MSI colorectal cancers compared with their GALNT7-Low counterparts, and this concurrent upregulation of Tn antigen and GALNT7 was also observed in pMMR/MSS colorectal cancers." (PMID 40824763, 2025). "Our study identified GALNT7 as a glycosyltransferase capable of stratifying patient outcomes and modulating PD-L1 levels, specifically within dMMR/MSI colorectal cancers." (PMID 40824763, 2025).